TGFBR3 (transforming growth factor beta receptor 3)
Diseases named in the same sentence as TGFBR3 in open-access papers (continued):
Sharing a sentence is not in itself a finding about the gene and the disease.
hemolysis (1 paper, 2020). Disruption of the integrity of the erythrocyte membrane causing release of hemoglobin. "The SCA individuals who carried the minor allele (T) of the TGFBR3 rs7526590 polymorphism also presented increased RDW and higher indirect markers of intravascular hemolysis, such as AST, IB, and LDH, as well as decreased ferritin levels, which is suggestive of an association with hemolysis." (PMID 33062074, 2020).
infarction (1 paper, 2023). A localised pathological necrosis of tissue resulting from obstruction of the blood supply usually by a thrombus, an embolus, or vascular torsion. "TGFBR3 signal can conduct and regulate apoptosis of myocardial cells after infarction." (PMID 36818340, 2023).
invasive carcinoma (1 paper, 2022). A carcinoma that is not confined to the epithelium, and has spread to the surrounding stroma. "TIMER2.0 was used to identify the correlation between EGFR and other gene expressions in breast-invasive carcinoma subtypes with purity adjustments such as FGF2, FGFBP1, TGFA, TGFBR3, and IGF1R in all BRCA patients." (PMID 36430763, 2022).
keloid (1 paper, 2022). An irregularly shaped, elevated mark on the skin caused by deposits of excessive amounts of collagen during wound healing. "Fibroblasts in keloids may specifically interact with macrophages and other MPs via TGFB2–TGFBR2, TGFB3– TGFBR3, CCL2-CCR1, and CCL2-CCR5 binding, which play inhibitory roles on the target cells." (PMID 35990663, 2022).
liver cancer (1 paper, 2024). An epithelial or non-epithelial malignant neoplasm that arises from the liver. "Downregulation of TGFBR3 expression can promote the EMT process of liver cancer by inducing activation of the SMAD2 and AKT pathways, thus promoting its progression." (PMID 39404708, 2024).
liver steatosis (1 paper, 2025). "Steatosis severity was associated with upregulation of COL5A3 and TP53I3, whereas upregulated RASGEF1B, S100A12, and TGFBR3 were linked to early-stage liver steatosis." (PMID 40689242, 2025).
lung adenocarcinoma (1 paper, 2021). A carcinoma that arises from the lung and is characterized by the presence of malignant glandular epithelial cells. "Similar outcomes were observed in lung adenocarcinomas with respect to TGFBR3, where INHA remained a strong negative predictor of survival in patients regardless of TGFBR3 expression levels." (PMID 33819300, 2021).
lymph node metastasis (1 paper, 2024). "The results showed that T classification and lymph node metastasis were risk factors for DFI, while high expression of TGFBR3 was a protective factor." (PMID 39404708, 2024).
membranous nephropathies (1 paper, 2025). "Transforming growth factor beta receptor type 3 (TGFBR3), one of the TGFβ receptors, was reported to be expressed in lupus nephropathy compared to other membranous nephropathies, although the positive rate was low." (PMID 41614843, 2025).
multiple sclerosis (1 paper, 2021). A progressive autoimmune disorder affecting the central nervous system resulting in demyelination. "TGFBR3 with multiple sclerosis and pulse pressure measurement." (PMID 34300314, 2021).
Myocardial fibrosis (1 paper, 2022). "The expression level of Tgfbr3 is negatively correlated with the degree of myocardial fibrosis." (PMID 35211156, 2022).
myocardial hypertrophy (1 paper, 2022). "The targeting interaction relationship between miR-27b-3p and Tgfbr3 appeared in our prediction results, which further indicated that the miR-27b-3p/Tgfbr3 axis may play a significant role in myocardial hypertrophy." (PMID 35211156, 2022). "Our findings suggest that three mRNAs (Col12a1, Thbs1, and Tgfbr3), four miRNAs (miR-20a-5p, miR-27b-3p, miR-342-3p, and miR-378a-3p), and four related circRNAs (circ_0002702, circ_0110609, circ_0013751, and circ_0047959) may play a key role in cardiac hypertrophy." (PMID 35211156, 2022).
oral squamous cell carcinoma (1 paper, 2022). "Similarly, the interaction between GDF10 and TGFBR3 regulates epithelial mesenchymal transition and tumor cell resistance through SMAD2/3 pathway in oral squamous cell carcinoma." (PMID 36714584, 2022).
osteomyelitis (1 paper, 2020). An acute or chronic inflammation of the bone and its structures due to infection with pyogenic bacteria. "The minor allele (A) of the TGFBR3 rs1805110 polymorphism was also associated with the occurrence of bone alterations, such as osteonecrosis of the femoral head and osteomyelitis, both clinical complications commonly seen in individuals with SCD." (PMID 33062074, 2020).
osteonecrosis (1 paper, 2020). A none disease characterized by death of bone tissue due to a lack of blood supply. "A previous study demonstrated that other polymorphisms in TGFBR3 were associated with osteonecrosis in individuals with SCD." (PMID 33062074, 2020).
ovarian failure (1 paper, 2024). "A previous study reported that mutations in TGFBR3 were highly correlated in human ovarian failure, suggesting that TGFBR3 could be used as a susceptibility marker gene for ovarian failure aetiology." (PMID 38955498, 2024).
peritonitis (1 paper, 2025). Inflammation of the peritoneum (tissue that lines the abdominal wall and covers most of the organs in the abdomen). "The group sampled 2 h following treatment exhibited a decrease in the concentrations of 35 proteins in animals subjected to laparoscopic lavage, while four proteins (TGFBR3, LPL, CCL2 and IL6) were found in elevated concentrations compared to time-matched peritonitis controls." (PMID 40102905, 2025).
pheochromocytoma (1 paper, 2021). "Interestingly enough, TGFBR3 mRNA levels were found to be underexpressed in pheochromocytoma patients, therefore, we are still in need of explanation of divergent expression levels between TGFBR3 mRNA and BSN-AS2 lncRNA." (PMID 33810219, 2021).
pneumonia (1 paper, 2020). An acute, acute and chronic, or chronic inflammation focally or diffusely affecting the lung parenchyma, caused by an infection in one or both of the lungs (by bacteria, viruses, fungi, or mycoplasma.). "With regard to clinical manifestations, the haplotypes have showed to be more informative than the polymorphisms individually analyzed; both the GG and CGG haplotypes of gene TGFBR3 were associated with the occurrence of pneumonia." (PMID 33149723, 2020). "Altogether, our results suggest that TGFBR3 haplotypes seem to be related to inflammation and the occurrence of pneumonia." (PMID 33149723, 2020).
prostate tumors (1 paper, 2021). "Several studies consistently report downregulation of TGFBR3 in prostate tumors, suggesting that it has an important role as a tumor suppressor gene." (PMID 33927218, 2021).
pulmonary fibrosis (1 paper, 2020). Chronic progressive interstitial lung disorder characterized by the replacement of the lung tissue by connective tissue, leading to progressive dyspnea, respiratory failure, or right heart failure. "There is downregulation of Sik2 from the IGF pathway, which is well known to have a role in aging, and of Tgfbr3, from the TGFβ pathway, which is important for lung development and pathogenesis of pulmonary fibrosis." (PMID 32591591, 2020).
salivary gland cancer (1 paper, 2017). A primary or metastatic malignant neoplasm that affects the major or minor salivary glands. "However, the role of high TGFBR3 levels in salivary gland cancer has not been investigated." (PMID 29084941, 2017).
serous ovarian cancer (1 paper, 2021). "Similar trends for TGFBFR3 expression were seen in TNBC and serous ovarian cancer groups where TGFBR3 was more expressed in the responders’ group for taxane regimens." (PMID 33819300, 2021).
soft tissue tumors (1 paper, 2014). "Interestingly, soft tissue tumors myxoinflammatory fibroblastic sarcoma (MIFS) and hemosiderotic fibrolipomatous tumor (HFLT) both share a translocation event resulting in rearrangements in TGFBR3 and MGEA5." (PMID 24550739, 2014).
tumor (105 papers, 2011 to 2025). "Decreased expression of TGFBR3 (former ETDL1) causes decreased TβRIII expression in tumor tissues, resulting in tumor progression due to increased invasiveness, angiogenesis, and a chance of metastasis." (PMID 40724805, 2025). "We found Somatic mutations in TGFBR1, TGFBR2, and TGFBR3 genes in primary tumor and metastases samples of long-responder patients." (PMID 34833459, 2021). "A decrease in tumor-associated TGFBR3 expression increased TGFβ-dependent upregulation of IDO in pDCs within the primary tumor and TDLN of murine models of breast cancer and melanoma." (PMID 33072086, 2020). "TGFBR3 expression is decreased during tumor progression, and this decrease is associated with poor prognosis." (PMID 32471132, 2020). "The most significant discoveries of stromal loss of TGFBR3 have been in dendritic cells, whereby the microenvironment becomes more immune-tolerant of the tumor." (PMID 27827906, 2016). "TGFBR3 has largely been studied in normal and cancerous cells and only recently investigated in tumor associated stromal cells." (PMID 27827906, 2016). "We also discovered that TGFBR3 is associated with tumor immune infiltration of PTC." (PMID 39404708, 2024). "In a separate study, it was also noticed that exosomal-miRNA-501-3p from tumor-associated macrophages (TAMs) enhance tumorigenesis and metastasis by affecting the transforming growth factor-beta receptor 3 (TGFBR3) and modulating the TGF-beta signaling pathway." (PMID 38927885, 2024). "To test this hypothesis, we first analyzed the integrated data from TCGA and found that TGFBR3 was expressed at low levels in high‐grade tumor tissues and that high levels of TGFBR3 were associated with favorable prognosis." (PMID 32491253, 2020). "Loss of TGFBR3 resulted in a tumor immune tolerant microenvironment." (PMID 27827906, 2016). "TGFBR3 was downregulated in our experiments which is also in line with previous reports which suggest that TGFBR3 is a tumor suppressor." (PMID 40017592, 2025). "Transforming growth factor beta receptor III (TGFBR3) has been shown to play a tumor-suppressive role in a variety of cancers." (PMID 39404708, 2024). "Lastly, TGFBR3 expression was found to be involved in tumor immune infiltration, highlighting its potential influence on immune dynamics within the tumor microenvironment in PTC." (PMID 39404708, 2024). "We first evaluated the correlation between TGFBR3 expression levels and tumor immunoinfiltration levels by using the tumor immune estimation resource (TIMER)." (PMID 39404708, 2024). "TGFBR3 plays a tumor-suppressive role in PTC progression by inhibiting the PI3K/AKT pathway and epithelial mesenchymal transformation." (PMID 39404708, 2024). "Fifteen (28%) of the TGFBR3L negative gonadotroph tumours and 10 (17%) of the TGFBR3L positive tumours also stained positive for TGFBR3 (p = 0.18)." (PMID 36952069, 2023). "It has been reported that TAM-derived exosomes transfer miR-501-3p to tumor cells, thus targeting TGFBR3 and facilitating the development of PDAC by activating the TGF-β signaling pathway." (PMID 35644825, 2023). "This microRNA inhibits the expression of the TGFBR3 gene, which is an important tumor suppressor, which stimulates an increase in the rate of cell migration and metastasis." (PMID 36910627, 2023). "In hypoxic glioblastoma, M2 macrophages transport EVs enriched with miR-501-3p to tumor cells, resulting in the downregulation of TGFBR3 expression in tumor cells." (PMID 38087360, 2023). "A decrease in TGFBR3 expression is observed in a number of tumors, which indicates the importance of this cascade in the context of tumor development." (PMID 36910627, 2023). "Proteoglycans in cancer is the most enriched pathway associated with MEIS1 and HOXB13 inhibition, inducing tumor suppression and DCN, LUM, and TGFBR3, as well as regulating growth factor, migration, and invasion signaling through receptor tyrosine kinases." (PMID 36661515, 2023).
tumor (continued). "Unsurprisingly, these genes have been previously associated with tumor growth and metastasis (NUAK1, TGFBR3, FGFBP2), as well as autoimmune disorders (PRSS23)." (PMID 37066364, 2023). "These genes have been previously associated with tumor growth and metastasis (NUAK1, TGFBR3, FGFBP2), as well as autoimmune disorders (PRSS23)." (PMID 38042785, 2023). "Both TGFB2 and TGFBR3 are directly involved in TGFβ signalling, which regulates many different aspects of tumour formation and progression." (PMID 37391533, 2023). "Another major tumor suppressor gene, TGFBR3, resides on chromosome 3, which is often deleted in EBV infected cells." (PMID 35804891, 2022). "MiR-501-3p in M2-Exos promotes tumor development by activating the transforming growth factor-β signaling pathway and inhibiting the tumor suppressor gene TGFBR3." (PMID 34368234, 2021). "We focused on TGFBR3, which is a well characterized tumor suppressor in several tumors and was highly reexpressed in the HELLS siRNA group." (PMID 33280236, 2021). "When the tumor progresses, the expression of TGFBR3 decreases and is well correlated with the poor prognosis of patients." (PMID 33280236, 2021). "Overexpression of TGFBR3 leads to cell proliferation arrest, deceased migration and invasion in vitro, and hinders angiogenesis and tumor growth in vivo." (PMID 33280236, 2021). "Two out of the 1701 DE genes found in the tumor mass of the TG-hLH-R-frt-200 mouse matched with the 10 more downregulated genes identified by Liu 2018 in EC, including Tgfbr3." (PMID 33893331, 2021). "Consistent with TGFBR3’s role as a tumor suppressor in many cancers, we found it to be a significant positive predictor of survival in all but two cancers (i.e., endometrial and all gastric subtypes)." (PMID 33819300, 2021). "TAMs have also been found to assist in promoting metastasis within PDAC tissue through the release of exosomal microRNA-501-3p (miR-501-3p), an inhibitor of the tumor suppressor TGFBR3, to activate the TGFβ signaling pathway and drive tumor cell migration." (PMID 35008355, 2021). "Increased TGFBR3 was predictive of response in all treatments and cancers we examined, further bolstering TGFBR3’s role as a negative regulator of tumor progression." (PMID 33819300, 2021). "One of the isoforms, ENST00000212355 (gene TGFBR3) from a combination associated with survival, is targeted by miRNA - hsa-let-7c-5p, which is known to be a tumor suppressor and acts by downregulating TGFBR3 post transcriptionally." (PMID 34674656, 2021). "We further unveiled the tumor suppressor TGFBR3 as a downstream target of HELLS, which is epigenetically silenced by HELLS." (PMID 33280236, 2021). "Exosomal miR-501-3p promotes cancer cell migration and invasion, as well as tumour formation and metastasis in vivo through regulation of TGFBR3 (transforming growth factor beta receptor 3)." (PMID 34064331, 2021). "Our study should facilitate the possibility of using TGFBR3-mediated tumor suppression for HNC treatment." (PMID 32471132, 2020). "Consistently, depletion of TGFBR3 blocked ligand-induced stimulatory effect on breast cancer cell motility, invasion, and xenograft tumor growth." (PMID 32471132, 2020). "We found that 70% (57/81) of these specimens showed a decrease in TGFBR3 protein expression in tumor tissues compared to adjacent healthy tissues." (PMID 32471132, 2020). "Overexpression of let-7a inhibits tube formation and reduces the migration rate of HUVECs by directly targeting TGFBR3, resulting in a defective TGFβ signaling pathway in these cells, decreased angiogenesis and tumor size." (PMID 33198082, 2020). "TGFBR3 is a tumor suppressor gene, which was found to decrease its expression to promote cancer cell migration and invasion." (PMID 31126066, 2019). "The expression level of TGFBR3 in TCGA database was further analyzed and the results revealed that there was a poor expression in the TGFBR3 gene in almost all tumor samples." (PMID 31307515, 2019).
tumor (continued). "Among these genes, PLP2 was upregulated and positively associated poorer survival, whereas LYVE1, FABP4, TGFBR3, and FXYD6 were downregulated and identified as tumor suppressor genes." (PMID 31803141, 2019). "The TGF-β superfamily co-receptor TGFBR3, which is regulated by miR-323b-3p, acts as a tumor suppressor in OS tumorigenesis and acts as a tumor promoter in pulmonary metastatic OS via activation of the epithelial–mesenchymal transition (EMT) program." (PMID 29991755, 2018). "At the early stage, miR-323b-3p inhibits the expression of TGFBR3, which acts as tumor suppressors in OS tumorigenesis by decreasing the TGF-β signaling." (PMID 29991755, 2018). "We suggested that TGFBR3 acts as a tumor suppressor during the early stage of OS development and becomes a tumor promoter during the late stages of metastases via activation of the EMT program." (PMID 29991755, 2018). "TGFBR3 can act as a tumor suppressor, which acts negatively on TGF-β signaling by binding to TGFBR1 and TGFBR2 separately, thereby inhibiting the TGFBR1/2 complex formation." (PMID 29084941, 2017). "For example, TGFBR3 is a potential tumor suppressor gene deleted in various cancers and with a role also in cell migration, invasion, and metastasis." (PMID 28544645, 2017). "The relationship of TGFBR3 to other key tumor–stroma molecular mediators is an essential direction for providing an insight into tumor microenvironment and determining novel options for early diagnosis and anticancer therapy." (PMID 27827906, 2016). "Recently, a role for TGFBR3 was found in the tumor microenvironment specifically in dendritic cells." (PMID 27827906, 2016). "Focusing on the genes in the TGF-β superfamily, we found that the most consistently changed gene expression in the tumor stroma among the TGF-β pathway related genes were a decrease in TGFBR3." (PMID 27827906, 2016). "Investigating TGF-β signaling components led to the finding that TGFBR3 was markedly decreased in tumor stroma compared with control stroma." (PMID 27827906, 2016). "Expression of the TGF-β type III receptor (TGFBR3) was greatly decreased in the tumor stroma compared to control healthy breast tissue." (PMID 27827906, 2016). "We investigated publicly available databases, and have identified that TGFBR3 mRNA levels are decreased in tumor stroma." (PMID 27827906, 2016). "The TGFBR3 levels were decreased in tumor stroma in 75% of patients while expression was intact across all the controls." (PMID 27827906, 2016). "Our study provides new insight to the role of TGFBR3 in the tumor microenvironment and perhaps helps resolve the current controversy of TGFBR3’s role in cancer." (PMID 27827906, 2016). "We next determined the levels of protein expression for several examples by flow cytometry of non-separated ascites samples and confirmed the preferential expression of S100A8/A9 and IL-8 in TAMs, and of LIFR and TGFBR3 in tumor cells." (PMID 27215396, 2016). "TGFBR3 gene expression from three controls and three tumor-derived stroma demonstrated a 44-fold decrease in TGFBR3 mRNA." (PMID 27827906, 2016). "In cancer cells it has been reported that TGFBR3 interacts with the p38 signaling pathway to coordinate disseminated tumor cells with TGF-β maintained in a stem/quiescent state." (PMID 27827906, 2016). "TGFBR3 has the potential to be a new key player in the tumor microenvironment, thus it is important to further characterize the physiological function of TGFBR3 in tumor–stroma interaction." (PMID 27827906, 2016). "Based on this rationale, four potential genes (JARID2, FRK, DR5 and TGFBR3) were selected from the databases of miRwalk, miRanda and TargetScan according to their potential functions in tumor suppressive processes." (PMID 27129166, 2016). "Currently, there are limited reports demonstrating the role of TGFBR3 in the tumor microenvironment." (PMID 27827906, 2016).